INS (insulin)
Diseases named in the same sentence as INS in open-access papers (continued):
Sharing a sentence is not in itself a finding about the gene and the disease.
type 2 diabetes (continued). "These agents selectively inhibit SGLT2 activity and promote urinary glucose excretion to reduce blood glucose without targeting the main pathology of type 2 diabetes mellitus (T2DM), such as insulin resistance and insulin hyposecretion." (PMID 28785316, 2017). "In our present study, deficiency of brain impaired insulin signaling pathway was found in the brain of T2D rats, which is consistent with our previous findings that showing impaired brain insulin signaling pathway in individuals with type 2 diabetes." (PMID 28225806, 2017). "We also identified novel HCV-induced alterations in the insulin-induced pathway, whose characterization may unravel unidentified mechanisms of HCV pathogenesis, notably in the context of the association of this virus with type II diabetes." (PMID 28480889, 2017). "The specific PPARγ ligands, thiazolidinediones (TZDs), are used in clinical practice to improve insulin sensitivity in type 2 diabetes mellitus (T2DM)." (PMID 27293418, 2016). "In addition, the type 2 diabetes risk allele (T) in TCF7L2 rs7903146 and rs12255372 has been linked to impaired insulin secretion and incretin action, and more specifically, a reduction in the second phase of GLP-1-induced insulin secretion." (PMID 27623947, 2016). "Thus, egg consumption seems to have either a null or beneficial effect on insulin sensitivity, and would therefore not be expected to elevate the risk of type 2 diabetes." (PMID 26993632, 2016). "Therefore, fenofibrate might be available to prevent the development of prediabetes and type 2 diabetes by improving insulin sensitivity and decreasing the secreting load of β-cells in hypertriglyceridemia patients with normal glucose tolerance." (PMID 27034649, 2016). "Also, Clps genetic variability is associated with insulin secretory function in non-diabetic humans, suggesting that Clps is a novel candidate gene associated with the development of type 2 diabetes." (PMID 27895803, 2016). "Thus, the increase in muscular DHT may contribute to the beneficial effects of regular resistance exercise on hyperglycemia and insulin sensitivity index in type 2 diabetes patients." (PMID 27832095, 2016). "According to a relevant review study, ARBs typically have trivial impact on basal glucose and insulin levels, particularly in lean animals, but nonetheless often improve glucose and insulin sensitivity, particularly in obese animals and/or models with type II diabetes." (PMID 27536242, 2016). "Protein expression of p-AKTser473 in muscle has shown to increase in response to insulin stimulation in muscle in healthy, obese, and type 2 diabetic subjects, but whether the insulin stimulated p-AKTser473 content differ between subjects displaying different metabolic conditions is not clear." (PMID 27777958, 2016). "In type 2 diabetes (referred to as non-insulin-dependent), beta cells are able to secrete enough insulin but the body cannot use the insulin effectively and attempts to compensate by making a higher quantity of insulin, causing insulin resistance." (PMID 27535125, 2016). "Therefore, part of the contribution of insulin resistance mechanisms to type 2 diabetes may be exerted via impaired BCAA metabolism." (PMID 27898682, 2016). "In another randomized trial involving 208 patients with type 2 diabetes receiving community-based insulin therapy in rural China, patients with peer support achieved greater reduction in HbA1c (0.60 % vs 0.32 %), knowledge of insulin usage, and self-management compared with patients with usual care." (PMID 27796780, 2016). "In terms of disease management, 17.5% (14.8% to 20.6%) of the participants managed type 2 diabetes with diet alone, 74.2% (70.6% to 77.5%) reported the use of oral hypoglycaemic agents, and 7.5% (5.6% to 10.0%) reported using both oral hypoglycaemic agents and insulin." (PMID 27294152, 2016).
type 2 diabetes (continued). "For type 2 diabetes, while proportions with type 2 diabetes specific (C10F) Read code in primary care were similarly high in those with a “probable” versus “possible” diagnosis (74% versus 63%), the latter were younger at diagnosis, and more likely to be on insulin alone." (PMID 27631769, 2016). "Type 2 diabetes (T2D) is the result of metabolic defects in insulin secretion and insulin sensitivity, yet most T2D loci identified to date influence insulin secretion." (PMID 27448167, 2016). "Therefore, the excessive sympathetic nervous system activation observed in type 2 diabetes may be attributed to increased insulin levels." (PMID 28066329, 2016). "Therefore, effective strategies to improve insulin sensitivity and/or to increase insulin secretion could greatly decrease prediabetes and subsequent type 2 diabetes." (PMID 27274905, 2016). "Given the influence of GPR21 on insulin signalling, a molecule that blocks its constitutive activity in a similar manner to the prospective native ligand could be a novel and powerful pharmacological strategy for the treatment of type 2 diabetes." (PMID 27243589, 2016). "A study reported that high levels of inflammatory cytokines appeared in early stage of T2DM and were capable of predicting the development of type 2 diabetes through diminishing insulin sensitivity." (PMID 27478850, 2016). "This study aimed to investigate the changes of hypothalamic NPY levels and the main hormones that regulate the synthesis and release of hypothalamic NPY, including insulin, leptin, and ghrelin, and may provide additional insights into the study of the pathogenesis of type 2 diabetes." (PMID 27867820, 2016). "However, when participants with type 2 diabetes on insulin medication (who may be considered to have more severe type 2 diabetes and could for that reason have more sedentary time) were excluded from the analysis, the results did not change." (PMID 26831300, 2016). "This is important, because it implies that very local insulin resistance, not only vascular complications peculiar to mammals, may contribute to impaired wound healing in type 2 diabetes, and that therefore local enhancement of IIS signalling at the wound itself could be beneficial." (PMID 27713427, 2016). "This suggests that the type 2 diabetes genes known so far have only minor effects on insulin secretion and that variation in these genes does not contribute much to the large difference in compensatory hypersecretion of insulin that is seen when NGT, IGT and diabetic individuals are compared." (PMID 27344314, 2016). "Interestingly, in type 2 diabetic patients, insulin infusion could significantly suppress the expression of CCL4 in mononuclear cells." (PMID 27553774, 2016). "Type 2 diabetes is chronic and progressive disease which may be the consequence of impaired insulin secretion by β-cells of pancreas, resistance of peripheral tissue to insulin action, and augmented hepatic glucose production." (PMID 27313954, 2016). "Therefore, unraveling the mechanisms by which GCs alter glucose homeostasis but more specifically insulin secretion could lead to a better understanding of the beta-cell alterations after GCs excess and more generally in type 2 diabetes." (PMID 26901633, 2016). "Additionally the thrifty phenotype hypothesis should be considered, as it suggests that poor nutrition in early life influence changes in glucose and insulin metabolism and can eventually lead to the development of type 2 diabetes." (PMID 27151384, 2016). "Thus, interactions between sulfatide and insulin crystals may have implications on disease pathogenesis in both type 1 and type 2 diabetes, which must be subject to further investigation." (PMID 26981544, 2016).
type 2 diabetes (continued). "Therefore, weight loss is the first-choice preventive and therapeutic intervention for type 2 diabetes; indeed, a reduction in body weight leads to improvement in insulin sensitivity and weight reduction is a good strategy for preventing the development of diabetes." (PMID 27591854, 2016). "Consequently, safe and effective modalities to improve systemic insulin sensitivity are direly needed not only for counteracting obesity-related type 2 diabetes but may also pave the way for novel therapeutic approaches in wasting diseases." (PMID 27827363, 2016). "In addition, Alzheimer’s disease and type 2 diabetes share impaired insulin signaling." (PMID 26978400, 2016). "Hypoglycemia is a common side effect of insulin therapy in both type 1 and type 2 diabetes mellitus (T1 and T2DM)." (PMID 26635724, 2015). "However, these participants had longer history of type 2 diabetes and were insulin dependent." (PMID 26272328, 2015). "Interestingly, metformin, an oral agent commonly prescribed to treat type 2 diabetes involved in the reduction of hepatic glucose production and/or insulin resistance, has shown to also decrease plasma DPP IV activity, limiting the inactivation of exogenously administered peptides." (PMID 26074958, 2015). "Interestingly, it has recently been reported that the well-known disturbed pulsatility of insulin secretion in type 2 diabetes is concomitant with disturbed glucagon pulsatility (higher pulse mass in patients with type 2 diabetes), possibly contributing to the hyperglucagonemia in these patients." (PMID 25961284, 2015). "Moreover, metabolic syndrome related to insulin resistance (IR) is a state in that insulin is higher than normal concentration and it plays an important role in the pathophysiology of most common human diseases such as type 2 diabetes mellitus, hypertension, and coronary heart disease." (PMID 26170888, 2015). "Whether these tentative conclusions can be generalized to the growing number of obese insulin-resistant adolescents at high risk of type 2 diabetes is not known but is worthy of study." (PMID 26066530, 2015). "Type 2 diabetes mellitus (T2DM) is a chronic condition characterised by elevated blood glucose levels as a result of resistance to the action of insulin." (PMID 26541516, 2015). "In addition, successive generational feeding of a high AGE diet to rodents results in descendants with increased adiposity, insulin resistance, impaired insulin signaling, and a proinflammatory phenotype, which further implicates dietary AGEs in the etiology of type 2 diabetes." (PMID 26223897, 2015). "Furthermore, Hspa5 was found increased in the pancreas of type 2 diabetes patients, indicating increased endoplasmic reticulum stress during this disease, and in a microarray-based gene expression study, Itpkc was found to be insulin-regulated." (PMID 25333294, 2015). "In type 2 diabetes, the development of hyperglycaemia is facilitated by pancreatic β-cell dysfunction, including a reduced incretin effect, which is defined as the relative increase in insulin secretion induced by oral versus intravenous glucose administration." (PMID 26567860, 2015). "Some of the more popular treatments for type 2 diabetes directly target circulating glucose concentrations and include pharmacological agents such as metformin, which reduces hepatic glucose production, or glibenclamide, which increases pancreatic insulin release." (PMID 26699937, 2015). "In a recent study we demonstrated that vildagliptin in combination with insulin reduced glucagon levels at hyperglycemia and sustained the glucagon counterregulation to hypoglycemia, which yielded lower glucose levels at hyperglycemia and prevention of hypoglycemia in type 2 diabetes." (PMID 26587020, 2015). "The purpose of this study was to evaluate the effectiveness and safety of an educational program for insulin self-adjustment based on SMBG in poorly controlled patients with type 2 diabetes (T2DM)." (PMID 25904987, 2015).
type 2 diabetes (continued). "Type 2 diabetes mellitus (T2DM) is a complex metabolic disorder characterized by hyperglycaemia arising from a combination of insufficient insulin secretion together with the development of insulin resistance." (PMID 26621478, 2015). "Similar to these findings in patients with IGT or type 2 diabetes, we show that shorter term (28 days) treatment of dysmetabolic monkeys with pioglitazone (3 mg kg-1 day-1) increases insulin-stimulated Rd by 62% and enhanced insulin-mediated suppression of EGP by 15%." (PMID 25954816, 2015). "Type 2 diabetes (T2DM) is characterized by elevated blood glucose levels caused by increased production of glucose in the liver and increased peripheral insulin resistance, which might eventually lead to a reduction in insulin secretion." (PMID 25993052, 2015). "A sizeable proportion of patients not on prior insulin could represent DKA associated with type 2 diabetes." (PMID 26715333, 2015). "Type 2 diabetes mellitus (T2DM) is a complex metabolic disorder resulting in insulin resistance of the peripheral tissues and impaired insulin secretion from the pancreas." (PMID 26193288, 2015). "Indeed, continuous subcutaneous infusion of GLP-1 or extendin-4 (a naturally occurring analogue of GLP-1) for 3 days in both insulin-resistant and type 2 diabetic rat models normalized their impaired trabecular architecture and promoted bone formation via an insulin-independent mechanism." (PMID 26177280, 2015). "Because of fundamental similarities in the insulin signaling pathway between worms and humans, genetic and molecular pathways that control metabolism in the worm could be highly informative for analysis of human metabolic diseases such as type 2 diabetes." (PMID 26218657, 2015). "There was an association between increasing severity of type 2 diabetes and increasing TB risk as indicated by time-dependent analyses comparing insulin users versus non-users in crude analyses with age adjustment (P = 0.020), but this relationship did not remain after full adjustment." (PMID 26048371, 2015). "Particularly in Brazil, a recent cross-sectional study including 5,692 outpatients with type 2 diabetes (T2DM) showed that the rate of poor glycemic control was 73% (90% among insulin-treated subjects)." (PMID 25904987, 2015). "However, several patients suffering from chronic myeloid leukaemia and Type 2 diabetes show a marked improvement in their glucose handling and completely stop administering exogenous insulin shortly after initiating their dasatinib-based therapy for the treatment of imatinib-resistant leukaemia." (PMID 25351958, 2015). "Given that type 2 diabetes is part of a continuum in which cardiovascular events are among the most severe complications, insulin or insulin resistance may be more valuable measurements in asymptomatic patients than HbA1c for assessing the degree of metabolic impairment." (PMID 26241903, 2015). "Furthermore, glucose-evoked Ca2+ signals and insulin secretion are impaired in mouse Cd38−/− pancreatic β cells, and Cd38−/− mice show glucose intolerance, and human CD38 autoantibodies and CD38 mutations have been shown to be associated with type-2 diabetes." (PMID 26152717, 2015). "As insulin and amylin are stored together and co-secreted by pancreas, amylin secretion would have a similar pattern as insulin by the damaged β cells in pancreas during chronic progression of type 2 diabetes, compensating by increasing its secretion and then diminishing its production." (PMID 25750761, 2014). "Therefore, it is anticipated that a combination of DPP-4 inhibitor and SU may synergistically stimulate insulin secretion and effectively ameliorate hyperglycemia in type 2 diabetes mellitus." (PMID 24578754, 2014). "Hence, FFAR4 agonists could become future insulin-sensitizing agents for the treatment of type 2 diabetes and other human insulin-resistant states." (PMID 25414667, 2014).
type 2 diabetes (continued). "Furthermore, considering the high prevalence of type 2 diabetes in Aboriginal and/or Torres Strait Islander populations a few may have been documented incorrectly with type 1 diabetes based on insulin administration." (PMID 24884679, 2014). "Most patients with type 2 diabetes, however, are overweight or obese right at the time of diagnosis and may gain further weight on treatment with drugs like sulphonylureas, glinides, thiazolidindiones and insulin." (PMID 24742256, 2014). "Data from an ecologic study suggest that fish intake may play a role in the prevention of type 2 diabetes, which is also supported by an animal experiment showing a favorable effect of long-chain omega-3 fatty acids, which are abundant in fish, on insulin resistance." (PMID 24511320, 2014). "However, compounds which improve insulin sensitivity and glucose intolerance are somewhat limited warranting the discovery and characterization of novel molecules targeting various pathways involved in the pathogenesis of type-2 diabetes." (PMID 24991576, 2014). "Combination therapy consisting of basal insulin and oral hypoglycemic agents (OHAs) is effective for the treatment of type 2 diabetes (T2DM) that cannot be adequately controlled using OHAs alone." (PMID 24684803, 2014). "The explanation for this reduction in secretion, as in type 2 diabetes, is still not clear, but may include: loss of islets; loss of beta cells; loss of insulin content; or reduced exocytic capacity." (PMID 24705605, 2014). "Finally, we provided novel exploratory information that fetuin-A may play a role in the pathogenesis of type 2 diabetes by affecting insulin secretion." (PMID 24643166, 2014). "A multicentre randomized parallel-group trial suggested that exenatide was more effective in improving β-cell function compared to insulin and piogltazone; hence, early initiation of β-cell-protective therapy with exenatide may halt the decline in β-cell function in type 2 diabetes." (PMID 25407893, 2014). "This most likely results from the effect on carbohydrate oxidation since we found that a lower carbohydrate oxidation rate during insulin stimulation was associated with a higher risk of type 2 diabetes, independent of age, sex, percentage body fat, AIR and non-oxidative glucose disposal rate." (PMID 24728127, 2014). "From the results obtained in the present study, add-on of sitagliptin to ongoing insulin therapy could be an effective and well-tolerated alternative to treat Japanese patients with type 2 diabetes who had been inadequately controlled by insulin with or without other OHAs." (PMID 27419209, 2014). "While some beneficial effects of taurine supplementation for reducing blood glucose and restoring insulin sensitivity have been found in type 2 diabetes, in type 1 diabetes, taurine might exert adverse effects on the glucose stability as a result of α-cell dysfunction." (PMID 25393115, 2014). "A salty diet could deteriorate insulin metabolism, and the drying of fish may accelerate the oxidation of polyunsaturated fatty acids, which in turn induces inflammation and is a known predictor of type 2 diabetes." (PMID 24870294, 2014). "The authors concluded that post-glucagon C-peptide estimation was a good predictor of Nigerians with type 2 diabetes who will likely require insulin for control and a single estimation of post-glucagon C-peptide levels may be a useful guide in predicting likelihood of the need for insulin." (PMID 25945127, 2014). "However, no data exist about the addition of these agents at the beginning of insulin treatment in type 2 diabetes while this could especially be interesting because it is during this period that considerable residual beta cell function is still present." (PMID 25175981, 2014).